DMD (dystrophin)
Diseases named in the same sentence as DMD in open-access papers (continued):
Sharing a sentence is not in itself a finding about the gene and the disease.
Duchenne muscular dystrophy (continued). "Duchenne muscular dystrophy (DMD) is a progressive, fatal muscle wasting disease caused by X-linked mutations in the dystrophin gene." (PMID 39669499, 2024). "Duchenne muscular dystrophy (DMD) is a severe muscle atrophy disease caused by mutations in the dystrophin gene." (PMID 39599754, 2024). "A deficiency in the shortest dystrophin-gene product, Dp71, is a pivotal aggravating factor for intellectual disabilities in Duchenne muscular dystrophy (DMD)." (PMID 38667332, 2024). "Duchenne muscular dystrophy (DMD) is an inherited X-linked recessive neuromuscular disease, which is caused by a mutations in the DMD gene resulting in deficiency of structural protein myotonic dystrophy proteins." (PMID 39233679, 2024). "Exome sequencing is not usually included as part of the patient diagnostic journey in Duchenne muscular dystrophy (DMD) because most individuals with this disease (70%) have a single-exon or multi-exon deletion or duplication in the DMD gene." (PMID 37989827, 2024). "Duchenne muscular dystrophy (DMD) is a rare X-linked genetic disorder that occurs as a result of mutations in the DMD gene encoding dystrophin, a protein found mainly in muscle cells as a component of the dystrophin–associated glycoprotein complex." (PMID 38078368, 2024). "Duchenne muscular dystrophy (DMD), an X-linked recessive disorder, stems from dystrophin gene mutations." (PMID 39703526, 2024). "The most common form of these inherited disorders is Duchenne muscular dystrophy (DMD), a degenerative, X-linked disease affecting both skeletal and cardiac muscles, caused by mutations in the dystrophin gene." (PMID 38542836, 2024). "Duchenne muscular dystrophy (DMD) is a X-linked neuromuscular disorder arising from mutations in the dystrophin gene, leading to a progressive muscle wasting and disability." (PMID 39535998, 2024). "Duchenne muscular dystrophy (DMD) is an X-linked recessive inherited disorder caused by mutations in the DMD gene encoding the protein dystrophin." (PMID 39337383, 2024). "Duchenne muscular dystrophy (DMD) is an X‐linked recessive myopathy due to mutations in the dystrophin gene." (PMID 38658324, 2024). "It would be interesting to verify whether the abnormal elevation of intracellular calcium concentration in dystrophin-deficient muscle, which contributes to disease progression in Duchenne muscular dystrophy, could be related to a lower amount of TA in Dmdmdx dystrophic muscle." (PMID 38343710, 2024). "Duchenne muscular dystrophy (DMD) is an inherited muscle wasting disease caused by loss of function mutations in dystrophin." (PMID 39298449, 2024). "Duchenne muscular dystrophy (DMD) is a fatal muscle wasting disease caused by mutations in the dystrophin gene resulting in cycles of muscle damage, inflammation and repair." (PMID 40292009, 2024). "Despite its notoriously mild phenotype, the dystrophin-deficient mdx mouse is the most common model of Duchenne muscular dystrophy (DMD)." (PMID 39716324, 2024). "Variation in the X-lined gene DMD, where dystrophin is mutated frequently, causes Duchenne muscular dystrophy (DMD), which is the most severe form." (PMID 39415830, 2024). "The archetypal syndromic cardiomyopathy is Duchenne muscular dystrophy, caused by mutations in the dystrophin (DMD) gene." (PMID 39519012, 2024). "Duchenne muscular dystrophy (DMD) is a severe X-linked neuromuscular disorder caused by mutations in the gene encoding for dystrophin, a protein expressed in the sarcolemma of the skeletal and cardiac muscles." (PMID 38630313, 2024). "The severity of brain comorbidities in Duchenne muscular dystrophy (DMD) depends on the mutation position within the DMD gene and differential loss of distinct brain dystrophin isoforms (i.e. Dp427, Dp140, Dp71)." (PMID 39718030, 2024).
Duchenne muscular dystrophy (continued). "Duchenne muscular dystrophy (DMD) is a severe X-linked disorder characterized by dystrophin gene mutations and mitochondrial dysfunction, leading to progressive muscle weakness and premature death of DMD patients." (PMID 39017908, 2024). "Duchenne muscular dystrophy (DMD) is an X-linked disease that results from mutations in the DMD gene, which codes for the protein dystrophin." (PMID 38050701, 2024). "Duchenne muscular dystrophy (DMD), caused by mutations in the dystrophin (DMD) gene, is associated with fatal muscle degeneration and atrophy." (PMID 38050706, 2023). "Duchenne muscular dystrophy (DMD) is a severe form of muscular dystrophy caused by mutations in the dystrophin gene." (PMID 37501163, 2023). "Duchenne Muscular Dystrophy (DMD) is a severe X-linked recessive disorder, affecting 1 out of 5,000 males born worldwide, caused by mutations in the DMD gene." (PMID 38288333, 2023). "Duchenne muscular dystrophy (DMD) is an X-linked degenerative disease of cardiac and skeletal muscles, as a consequence of mutations in the dystrophin gene." (PMID 36891137, 2023). "Duchenne muscular dystrophy (DMD) is a serious and progressive inherited human myopathy derived from mutations in X-linked recessive gene encoding dystrophin, a membrane protein that maintains structural stability and integrity of myofiber." (PMID 36713032, 2023). "Duchenne muscular dystrophy (DMD) is caused by mutations in the DMD gene that disrupt the open reading frame and thus prevent production of functional dystrophin proteins." (PMID 38137463, 2023). "Duchenne muscular dystrophy (DMD) is an X-linked, recessive, neuromuscular disorder resulting from DMD gene mutations (deletions, duplications, nonsense mutations) causing a loss of dystrophin protein and function in striated muscle." (PMID 37005891, 2023). "Duchenne muscular dystrophy (DMD) is a fatal X-linked recessive disease of progressive muscle weakness and wasting caused by the absence of dystrophin protein." (PMID 37215149, 2023). "Duchenne muscular dystrophy (DMD) is characterized by progressive muscle damage resulting from a mutation in the dystrophin gene that disrupts dystrophin function." (PMID 37822297, 2023). "Duchenne muscular dystrophy (DMD) is an X-linked muscular disease with mutations in the dystrophin gene." (PMID 37950170, 2023). "Duchenne muscular dystrophy (DMD) and Becker muscular dystrophy (BMD) are X-linked genetic disorders caused by variants in the DMD gene, which encodes the dystrophin protein and is required for structural stability of the sarcolemma." (PMID 37426526, 2023). "Several proof‐of‐concept investigations utilizing animal models of Duchenne muscular dystrophy (DMD), caused by mutations in the DMD gene, have successfully demonstrated the restoration of functional dystrophin via gene editing." (PMID 40625571, 2023). "Duchenne muscular dystrophy (DMD) is characterized by loss of dystrophin in muscle, however patients also have variable degree of intellectual disability and neurobehavioural co-morbidities." (PMID 35136951, 2023). "Duchenne muscular dystrophy (DMD) is an X chromosome-linked disease caused by various mutations in the gene encoding the dystrophin protein." (PMID 37239853, 2023). "Duchenne muscular dystrophy (DMD) is a devastating, severe, and progressive X-linked disorder in which mutations in the dystrophin gene lead to loss of functional dystrophin protein, making the muscle fibres prone to damage after skeletal muscle contraction." (PMID 37813938, 2023). "Duchenne muscular dystrophy (DMD) is a dystrophinopathy caused by mutations in the DMD gene, a gene located on the X chromosome, which is responsible for coding the dystrophin." (PMID 36983602, 2023). "Exon deletion mutations in the dystrophin are among the most common causes of Duchenne muscular dystrophy (DMD)." (PMID 36895064, 2023).
Duchenne muscular dystrophy (continued). "Duchenne muscular dystrophy (DMD) is a severe X-linked recessive disorder caused by mutations in the dystrophin gene and consequent complete loss of dystrophin protein expression." (PMID 37435300, 2023). "Duchenne muscular dystrophy (DMD) is a severe and progressive neuromuscular disorder characterized by insufficient production of dystrophin due to mutations in the dystrophin gene." (PMID 38201863, 2023). "One of the most common X-linked neuromuscular disorders, Duchenne Muscular dystrophy (DMD), is caused by mutations in the dystrophin-encoding gene DMD and is inherited in a recessive X-linked manner." (PMID 36675224, 2023). "Duchenne muscular dystrophy (DMD) is an X-linked progressive muscle degenerative disease caused by mutations in the dystrophin gene, resulting in death by the end of the third decade of life at the latest." (PMID 37240001, 2023). "Duchenne muscular dystrophy (DMD) is a fatal genetic disease stemming from mutations in the DMD gene located on the X-chromosome." (PMID 36986639, 2023). "Loss-of-function mutations in the gene encoding dystrophin result in Duchenne Muscular Dystrophy (DMD) and mutations in the sarcoglycan genes cause subtypes of Limb Girdle Muscular Dystrophy (LGMD)." (PMID 37746696, 2023). "The loss of full-length dystrophin results in Duchenne muscular dystrophy (DMD), while a partial loss, leading to a shortened protein with a reduced function, results in clinically milder Becker muscular dystrophy (BMD)." (PMID 37374149, 2023). "Duchenne muscular dystrophy (DMD) is an inherited disorder that results in increasing muscle degeneration and muscle weakness because of a mutation in the dystrophin protein." (PMID 37384074, 2023). "Duchenne muscular dystrophy (DMD) is caused by a genetic defect leading to impaired dystrophin synthesis in muscle." (PMID 37928155, 2023). "Exon-skipping therapy is a promising treatment strategy for Duchenne muscular dystrophy (DMD), which is caused by loss-of-function mutations in the DMD gene encoding dystrophin, leading to progressive cardiomyopathy." (PMID 38028197, 2023). "Duchenne muscular dystrophy (DMD) is a devastating disease that affects approximately 1 in 5000 male births and is caused by mutations in the dystrophin gene." (PMID 37894981, 2023). "Duchenne muscular dystrophy (DMD) is an X-linked disease caused by mutations in DMD gene and loss of the protein dystrophin, which ultimately leads to myofiber membrane fragility and necrosis, with eventual muscle atrophy and contractures." (PMID 38044436, 2023). "Duchenne muscular dystrophy (DMD) is a progressive muscle wasting disorder caused by mutations in the DMD gene encoding the protein dystrophin." (PMID 36609344, 2023). "Duchenne muscular dystrophy (DMD) is an X-linked severe muscle degenerative disease caused by mutations in the dystrophin gene." (PMID 37889296, 2023). "Another involved disease in CRISPR-Cas9 research was Duchenne muscular dystrophy (DMD), a severe X-linked myopathy caused by mutations in the human DMD gene which results in a defective dystrophin protein." (PMID 37545694, 2023). "Duchenne muscular dystrophy (DMD) is a lethal X-linked disease caused by mutations in the dystrophin gene, leading to muscle degeneration and wasting." (PMID 37999748, 2023). "Duchenne muscular dystrophy (DMD), the most common and severe form of MD, is caused by mutations in the dystrophin (DMD) gene." (PMID 37892218, 2023). "Duchenne muscular dystrophy (DMD) is a severe muscle disease caused by impaired expression of dystrophin." (PMID 36265896, 2023). "In the same line, mitochondrial dynamics, and ROS production play crucial roles in the pathogenesis of Duchenne muscular dystrophy (DMD), a genetic skeletal muscle disorder characterized by mutations in the gene that encodes dystrophin." (PMID 37627619, 2023).
Duchenne muscular dystrophy (continued). "The gene dystrophin is responsible for Duchenne muscular dystrophy (DMD), a grave X-linked recessive ailment that results in respiratory and cardiac failure." (PMID 37569835, 2023). "Duchenne muscular dystrophy (DMD) is a devastating X-linked muscular disease, caused by mutations in the DMD gene encoding Dystrophin and affecting 1:5000 boys worldwide." (PMID 37858263, 2023). "Duchenne muscular dystrophy (DMD) is a genetic disorder produced by mutations in the dystrophin gene and characterized by early onset progressive muscle weakness leading to irreversible severe disability." (PMID 37673877, 2023). "It is a drug used to treat some types of Duchenne muscular dystrophy (DMD), caused by specific mutations in the dystrophin gene." (PMID 36833241, 2023). "Duchenne muscular dystrophy (DMD) is a degenerative, neuromuscular disease caused by mutations that disrupt the open reading frame of the X-linked dystrophin gene and occurs in approximately one per 3500 to 5000 males worldwide." (PMID 37670674, 2023). "ASOs are also useful for generating a partially functional truncated protein by causing exon skipping to restore in-frame reading of the dystrophin gene to achieve a treatment for Duchenne muscular dystrophy (DMD)." (PMID 36835961, 2023). "Duchenne muscular dystrophy (DMD) is a hereditary neuromuscular disorder caused by mutation in the dystrophin gene (DMD) on the X chromosome." (PMID 37772130, 2023). "Duchenne muscular dystrophy (DMD), a progressive muscle disease caused by the absence of functional dystrophin protein, is associated with multiple cellular, physiological, and metabolic dysfunctions." (PMID 37811713, 2023). "Duchenne muscular dystrophy (DMD) is an X-linked progressive muscle degenerative disease caused by mutations in the dystrophin gene with an estimated prevalence between 1.3 and 2.1 per 10,000 live male births." (PMID 37240001, 2023). "Duchenne muscular dystrophy (DMD) is an X-linked disease characterized by progressive muscle weakness due to mutations in the DMD gene." (PMID 36932329, 2023). "Duchenne muscular dystrophy (DMD), a fatal, X-linked, muscle-wasting disease with no cure, is caused by mutations in the dystrophin (DMD) gene." (PMID 38050706, 2023). "Duchenne muscular dystrophy (DMD) is a severe, progressive and lethal X-linked disease caused by mutations in the dystrophin gene that affects 1 in 3600–6000 live male births." (PMID 37707670, 2023). "Duchenne muscular dystrophy (DMD), caused by loss-of-function mutations in the dystrophin gene, leads to progressive muscle degeneration and results in heart and respiratory failure." (PMID 36771073, 2023). "Duchenne muscular dystrophy (DMD) is the most common fatal muscle disease, with an estimated incidence of 1/3500–1/5000 male births, and it is associated with mutations in the X-linked DMD gene encoding dystrophin, the largest known human gene." (PMID 36012442, 2022). "Duchenne muscular dystrophy (DMD) is a lethal X-linked recessive disease caused by mutations in the DMD gene coding for dystrophin protein." (PMID 35419381, 2022). "Duchenne muscular dystrophy (DMD) is an X-linked, recessive, degenerative neuromuscular disease caused by mutations in the dystrophin (DMD) gene that disrupt the messenger RNA (mRNA) open reading frame, preventing translation of the dystrophin protein." (PMID 34788571, 2022). "Gene therapy using the adeno-associated virus (rAAV) to deliver mini/micro- dystrophin is the current promising strategy for Duchenne Muscular Dystrophy (DMD)." (PMID 36360257, 2022). "Duchenne muscular dystrophy (DMD) is an X-linked disorder affecting approximately 0.02% live male births; it is caused by gene mutations in the cytoskeletal macromolecule dystrophin that lead to negligible expressed protein)." (PMID 36099033, 2022).
Duchenne muscular dystrophy (continued). "Oxidative stress is implicated in the pathophysiology of Duchenne muscular dystrophy (DMD, caused by mutations in the dystrophin gene), which is the most common and severe of the muscular dystrophies." (PMID 35249268, 2022). "Duchenne Muscular Dystrophy (DMD) is a rare X-linked disorder which leads to the progressive degeneration of muscle tissues due to the lack or deficiency of the protein dystrophin." (PMID 35241084, 2022). "Duchenne muscular dystrophy (DMD) is the most common and cureless muscle pediatric genetic disease, which is caused by the lack or the drastically reduced expression of dystrophin." (PMID 35216132, 2022). "Duchenne muscular dystrophy (DMD) is caused by loss of function mutations in DMD, encoding dystrophin." (PMID 36123393, 2022). "Duchenne muscular dystrophy (DMD) is an incurable X-linked inherited neuromuscular disorder and is caused by mutations in the dystrophin gene (DMD)." (PMID 35711930, 2022). "Duchenne Muscular Dystrophy (DMD) is a rare X-linked genetic disorder, caused by mutations in the dystrophin gene." (PMID 35055145, 2022). "Duchenne muscular dystrophy (DMD) is an X-linked genetic neuromuscular disorder resulting in dystrophin protein mutation." (PMID 35725473, 2022). "Duchenne muscular dystrophy (DMD) is a life-threatening neuromuscular disease that results from mutations in the dystrophin gene on the X chromosome, leading to severe and progressive muscle destruction." (PMID 35886024, 2022). "Duchenne muscular dystrophy (DMD), an X-linked childhood-onset muscular dystrophy caused by loss of the protein dystrophin, can be associated with neurodevelopmental, emotional and behavioural problems." (PMID 35439255, 2022). "Mutations in the dystrophin gene cause Duchenne muscular dystrophy (DMD), a common muscle disease that manifests with muscle weakness, wasting, and degeneration." (PMID 36385509, 2022). "(B) Duchenne muscular dystrophy (DMD) is a primitive myopathy linked to X chromosome, in particular, to the DMD gene localized on region Xp21 that codifies for an important muscular protein called “dystrophin”." (PMID 36012138, 2022). "Loss of function mutation of the dystrophin gene results in Duchenne Muscular Dystrophy (DMD), underscoring the importance of DGC function in muscle physiology." (PMID 35330913, 2022). "Null mutations in the Dp427 isoform of the dystrophin gene result Duchenne Muscular Dystrophy (DMD)." (PMID 35762211, 2022). "Duchenne muscular dystrophy (DMD) is a severe muscle degenerative disease caused by a dystrophin mutation that results in ambulation loss, respiratory dysfunction, and premature death." (PMID 36147742, 2022). "Duchenne muscular dystrophy (DMD) is a fatal genetic disease affecting children that is caused by a mutation in the gene encoding for dystrophin." (PMID 35205302, 2022). "Duchenne muscular dystrophy (DMD) is a fatal X-linked disorder, caused by one or more mutations in the DMD gene, which encodes dystrophin, an actin-binding cytoskeletal protein." (PMID 36372234, 2022). "Duchenne muscular dystrophy (DMD) is a neurodevelopmental disorder primarily caused by the loss of the full-length Dp427 dystrophin in both muscle and brain." (PMID 36293496, 2022). "Duchenne muscular dystrophy (DMD) is a devastating, progressive X-linked neuromuscular disorder caused by mutations in the gene dystrophin (DMD) for which there is currently no cure." (PMID 35327337, 2022). "Duchenne muscular dystrophy (DMD) is a debilitating and lethal neuromuscular disorder caused by mutations in the DMD gene located on the X chromosome." (PMID 36164827, 2022). "Duchenne muscular dystrophy (DMD), closely linked with the altered expression or null mutation of dystrophin in cardiac and skeletal muscles, are frequently complicated by cardiac hypertrophy and dilated cardiomyopathy." (PMID 36428995, 2022).